FLT1 (fms related receptor tyrosine kinase 1)
Diseases named in the same sentence as FLT1 in open-access papers (continued):
Sharing a sentence is not in itself a finding about the gene and the disease.
FLT1 also shares sentences with these, for which no sentence is quoted: age-related macular degeneration (14 papers); fetal growth restriction (12); liver cancer (11); non-small cell lung carcinoma (10); Lewis lung carcinoma (7); thyroid cancer (7); gastrointestinal stromal tumor (6); metastatic colorectal cancer (6); metastatic melanoma (6); colorectal tumor (5); gastric ulcer (5); head and neck squamous cell carcinoma (5); infantile hemangioma (5); ischemic stroke (5); ovarian tumor (5); soft tissue sarcoma (5); squamous cell carcinoma (5); Stillbirth (5); acute pancreatitis (4); B-cell chronic lymphocytic leukemia (4); Coronary artery disease (4); gastric tumor (4); liver fibrosis (4); pancreatic adenocarcinoma (4); thymic carcinoma (4); thymoma (4); acute myocardial infarction (3); asthma (3); benign prostatic hyperplasia (3); choroidal neovascularization (3).
A further 206 diseases each share a sentence with FLT1 in 3 papers or fewer.